CD44 (CD44 molecule (IN blood group))
Diseases named in the same sentence as CD44 in open-access papers (continued):
Sharing a sentence is not in itself a finding about the gene and the disease.
ovarian carcinoma (continued). "The binding of HA to CD44 triggers direct cross-signaling between different signaling pathways including HER2, c-src kinase and ERK and it is this function which is thought to be involved in increased motility, adhesion, and invasion of cancer cells as well as tumor growth, including ovarian cancer." (PMID 21541039, 2011). "Further subgroup analysis showed that in early-stage ovarian cancer (FIGO stage I/II), patients with high number of CD44+ EOC stem cells (>20%) had significantly shorter progression-free survival compared to patients with a low number of CD44+ cells EOC stem cells (<20%) (P = 0.026)." (PMID 21904548, 2011). "Since high levels of CD44+ EOC stem cells correlated with poor prognosis in early stage ovarian cancer but not in patients with advanced FIGO stage, it is possible that the high level of EOC stem cells in stage I, and II resulted in the observed significance in the multivariate analysis." (PMID 21904548, 2011). "However, despite being a negative prognostic factor for ovarian cancer patients, CD44 widespread expression makes it a suitable target for nanoparticle-mediated therapy, as it can overcome drug resistance and improve drug delivery and accumulation in tumor tissue." (PMID 37287910, 2023). "As reported, CD44 could not serve as prognosis predictor of ovarian cancer." (PMID 33303029, 2020). "Therefore, although CD44 is crucial for the invasion of ovarian cancer, it may not be the only determinant of invasive capacity of different ovarian cancer cell lines." (PMID 31497537, 2019). "CD44 cell surface marker, SP cells and ALDHBr cells have been reported as stem cell markers for gynecological malignancies using cell lines OVCAR3, HEC-1 and other lines and primacy samples, and CSC/CIC research may improve the outcome of advanced ovarian cancer patients." (PMID 23967051, 2013). "We used multiple ovarian cancer cell lines to validate the binding of the selected XAs and motifs, including CD44-positive IGROV and SKOV3 cell lines, as well as the CD44-negative A2780 cell line." (PMID 40001633, 2025). "There were significantly higher levels of CD44, CD133, and VDR expression in HGSC than in non-HGSC ovarian cancers (p = 0.015, p = 0.035, and p = 0.001, respectively)." (PMID 40332380, 2025). "In contrast to CD44, the expression of CD133 was not significantly increased in high-grade ovarian cancers compared to APTs (p = 0.157) or BOTs (p = 0.060)." (PMID 40332380, 2025). "CD44-expressing ovarian cancer stem cells are more resistant to platinum salts and to paclitaxel (PTX) than CD44-negative cells." (PMID 35814444, 2022). "We have observed upregulation of CD36 in SKOV-3-R, a cisplatin-selected subline of SKOV-3 ovarian cancer cells, a multi-drug resistant subline and which, unlike the parental line, forms spheres in stem cell medium and expresses ALDH1A, CD117 and CD44." (PMID 31661927, 2019). "According to CD44 positivity these authors distinguished two types of tumor cells: type I ovarian cancer cells, CD44+ALDH1+, MyD88+, large and non-dividing; type II ovarian cancer cells, CD44−, ALDH1−, MyD88−, small and rapidly dividing." (PMID 29389895, 2018). "Molecular factors not included in our array, such as gp100, ERCC, CD44, CD147, c-met, IL-6, ALDH, CD117 and BMP2 have also been studied in the context of chemoresistance in ovarian cancer." (PMID 27258020, 2016). "Cancer cells overexpressing CXCR4 and CD133 were evaluated in fresh primary human ovarian cancer revealing extremely variable levels of CXCR4+/CD133+ and CD24+/CD44+ positive cells, without significant differences among the group of patients." (PMID 26020117, 2015). "In contrast, in patients with advanced-stage ovarian cancer (FIGO stage III/IV), the number of CD44+ EOC stem cells did not correlate with progression-free survival (P = 0.95, data not shown)." (PMID 21904548, 2011).
ovarian carcinoma (continued). "Although we have found that, for these reasons, EMT-like changes does not indicate prognosis in ovarian cancer, some of our results are consistent with the hypothesis that EMT is stimulated by CD44 and MMP-14 expression." (PMID 27590006, 2016). "However, changes in tumor volume in mice treated with either the combination of HA-PEI/HA-PEG/non-specific siRNA CD44 targeted nanoparticle and paclitaxel or the combined naked MDR1 siRNA and paclitaxel was similar to that with paclitaxel treated alone in this ovarian cancer MDR model." (PMID 25687880, 2015).
colorectal cancer (379 papers, 1996 to 2026). A primary or metastatic malignant neoplasm that affects the colon or rectum. "Multiple isoforms of CD44 have been implicated in malignant progression across diverse tumor types, including colorectal cancers, pancreatic cancers, prostate cancers, head and neck squamous cell carcinomas, breast cancers, and gliomas." (PMID 41009730, 2025). "CD44 is implicated in various types of cancers, such as breast cancer, prostate cancer, colorectal cancer, and pancreatic cancer." (PMID 40422189, 2025). "This is in contrast to a report describing CD44 to associate with less aggressive disease in colorectal cancer." (PMID 39888143, 2025). "Jiang and colleagues have shown that upregulated CD276 in primary colon adenocarcinoma can enhance the expression of CD133 and CD44 associated with the EMT in colorectal cancer." (PMID 38398141, 2024). "Sometimes, e.g., in the case of colorectal cancer, CD44 isoform 3 has been shown associated with both poor prognosis/higher recurrence rate and good prognosis/lower recurrence rate, pointing to the possible greater significance of the ratio of CD44 isoforms." (PMID 38106992, 2023). "In colorectal cancer, related experiments also proved that the interaction between tumor-associated macrophages and CD44-positive cancer cells via SPP1-CD44 is important for colorectal cancer progression." (PMID 37188183, 2023). "Increased CD44 expression in colorectal cancer cells was shown to be linked to increased AKT expression by the superimposition of targeted proteomic analysis on transcriptomic analysis." (PMID 37083591, 2023). "Several previous studies have demonstrated that CD44 enhances colorectal cancer cell migration and invasion and is associated with tumor progression and distant metastasis of colorectal cancer." (PMID 35590122, 2022). "In one study of 946 colorectal cancer patients and 989 controls, SNPs in 3′ UTR of CD44 genes revealed an association with increased susceptibility of colorectal cancer." (PMID 35330456, 2022). "For example differing isoforms of CD44 + stem cells have been found to be associated with opposing prognostic outcomes in colorectal cancer." (PMID 35583632, 2022). "According to immunohistochemistry analysis of colorectal cancer tissues, CD44 protein abundance was directly substantially associated with tumor grading, peritumoral budding, lymph node metastasis as well as advanced cancer stage." (PMID 33303029, 2020). "The expression of alternatively spliced CD44 adhesion molecules has been implicated in the pathogenesis and metastasis of colorectal cancer." (PMID 32503434, 2020). "An overexpression of CD44 is also associated with unfavorable prognosis in colorectal cancer patients." (PMID 33330453, 2020). "It implies that CC-CAFs potentially enhance colorectal cancer metastasis by up-regulation of CD44 whose association with metastasis has been observed in our clinical specimen and orthotopic liver metastatic model." (PMID 31367190, 2019). "CD44 isoform containing variant exon v6 (CD44v6) has also been reported to play an important role in the progression, metastasis, and prognosis of colorectal cancer (CRC)." (PMID 31139149, 2019). "The associations between CD44 rs187115 polymorphism and clinical characteristics of colorectal cancer." (PMID 31682231, 2019). "The expression of the CD133+ CD54+ CD44+ cellular subpopulation of circulating tumor cells has been identified as significantly associated with liver metastasis of colorectal cancer." (PMID 30282914, 2018). "In the previous study, we had showed the expression of CD133+CD54+CD44+ cellular subpopulation of circulating tumor cells (CTCs) was significantly associated with liver metastasis of colorectal cancer (CRC)." (PMID 29105339, 2017).
colorectal cancer (continued). "Based on these theories, we investigated the changes in cancer stem cell population expressed CD133 and CD44, which are well known colorectal cancer stem cell surface markers caused by 5-Fu, metformin, and combination treatments." (PMID 28915611, 2017). "In conclusion, miR-139-5p downregulated NOTCH1 signaling to reverse CD44+/CD133+-associated MDR in colorectal cancer cells." (PMID 27738333, 2016). "Patients with the CD44 polymorphism rs13347TT genotypes was associated with the increased risk of colorectal cancer between the cases and controls." (PMID 26010608, 2015). "The presence of this CD44 isoform on colorectal cancer cells was linked to tumor progression in ApcMin/+ mice." (PMID 25904917, 2015). "In the current study, we investigated if polymorphisms in the 3’-untranslated region (UTR) of CD44 are associated with increased susceptibility to colorectal cancer (CRC) by conducting a case-control study of 946 CRC patients and 989 cancer-free controls." (PMID 26010608, 2015). "Based on the important role of CD44 splice variants in colorectal cancer progression and metastasis, we evaluated the use of CD44v6 expression to detect and assess the metastatic potential of colorectal tumour cells circulating in peripheral blood." (PMID 10755402, 2000). "Moreover, the detection of CD133+ and CD44+ in patient serum has been correlated with relapses and metastases in colorectal cancer, linked to the presence of latent CSCs." (PMID 40226589, 2025). "Similarly, reduced CD44 expression in colorectal cancer is linked to deeper tumor invasion and lymph node metastasis." (PMID 41514534, 2025). "In particular, CD44+ colorectal cancer stemness was notably increased by CTGF deficiency." (PMID 39518936, 2024). "Several isoforms of the CD44 are associated with malignant progression in various tumors, including head and neck squamous cell carcinomas (HNSCCs), pancreatic cancers, breast cancers, gliomas, prostate cancers, and colorectal cancers (CRC)." (PMID 37185762, 2023). "Indeed, the high ratio of CD44 isoform 4/CD44 variant exon v9 in patients with colorectal cancer shows a significantly poorer prognosis than the low CD44 isoform 4/CD44 variant exon v9 ratio." (PMID 38106992, 2023). "We found that miR-6511b-5p might act as a diagnostic marker and contribute to the treatment of pMMR colorectal cancer through regulation of the BRG1/CD44 axis." (PMID 35590122, 2022). "The prospective role of CD44 cell adhesion molecule in tumorigenic potential and its association with the proliferative activity and apoptotic status of Egyptian patients with ulcerative colitis (UC) and colorectal cancer (CRC) were investigated in this study." (PMID 34837915, 2021). "For the identification of CSCs, several putative markers such as transmembrane glycoprotein (CD133) and the cell-surface glycoprotein (CD44) were reported to be expressed in colorectal cancer and correlated with high-risk cases and a poorer survival rate of colorectal cancer patients." (PMID 33445526, 2021). "Based on the expression of CD44 and CD133, two well-recognized cell surface markers for CSC identification, we tried to separate HCT8 colorectal cancer cells into different subpopulations and then investigated how the expression of CD44 and CD133 associated with doxorubicin (DXR) resistance." (PMID 32849878, 2020). "We investigated whether CD44 rs187115 polymorphism is associated with colorectal cancer (CRC) risk and prognosis." (PMID 31682231, 2019).
colorectal cancer (continued). "At least, some of the CD44 variants are associated with cancer aggressive behavior, such as radioresistance, chemoresistance and metastases, and correlate with poor prognosis in a variety of human malignancies, including colorectal cancer." (PMID 29064439, 2017). "Interestingly, OPN secretion by TAMs is stimulated by CD44+ colorectal cancer cells, and the induction of OPN is closely associated with CD44 expression." (PMID 28769537, 2017). "This recent finding is significant because CD44 variant isoform expression is correlated with tumor progression in colorectal cancer and high Wnt activity, which is the signaling pathway known to control colorectal cancer progression." (PMID 25954275, 2015). "In this present molecular epidemiological study, we investigated the associations of three SNPs in the 3’-UTR of CD44 gene with risk of colorectal cancer in Chinese population and found that the rs13347C/T was significantly associated with an increased risk of CRC." (PMID 26010608, 2015). "Furthermore, we report a unique roster of all expressed CD44 variant isoforms characteristic to colorectal cancer." (PMID 23151220, 2012). "Therefore, it could be concluded that rs13347C/T in 3′ UTR of CD44 is associated with an increased risk and susceptibility of colorectal cancer, and the change in hsa-mir-509-3p binding in rs13347 position influenced the expression levels of CD44." (PMID 35330456, 2022). "Similarly, other studies reported CD44 as a major STn carrier in colorectal cancer 61, suggesting that CD44 glycosylation may be implicated in cellular adhesion alterations." (PMID 32308758, 2020). "In addition to enabling cell survival, CD44 has been confirmed as an initiator of tumorigenesis and molecular marker for cancer stem cells and has been linked with cell invasion and metastasis of colorectal carcinoma cells." (PMID 32456134, 2020). "In addition, increased CD44 expression in colorectal cancer is associated with the aggressive behavior of colorectal cancer, indicating that it may play potential roles in cancer stemness traits." (PMID 31109321, 2019). "In addition, Claudin-7 was shown to be associated with CD44 in colorectal cancer cells." (PMID 30874545, 2019). "Previous studies have shown that 5‐FU‐resistant colorectal cancer cells exhibit elevated expression of stemness‐associated markers, including NOTCH1, CD44, ALDHA1, Oct4, SOX2, and Nanog." (PMID 41543046, 2026). "As an illustration, in cases of colorectal cancer, tumor development typically requires the introduction of 200–500 EpCAM-high/CD44+ cells; in contrast, injection of 104 EpCAM-low/CD44− cells cannot induce tumor formation." (PMID 40647400, 2025). "Some studies suggest that combining CD133 with other CSCs markers, such as CD44, provides an optimal CSCs-specific marker for liver and colorectal cancers." (PMID 39940889, 2025). "Butyrate is considered a pro-ferroptotic agent, thus suppressing CD44 and xCT expression in colorectal cancer stem cells." (PMID 39859345, 2025). "Bisebracteolasins A and B exhibit inhibitory activity against the CD44+ colorectal cancer stem cell line P6C, with IC50 values of 16.48 and 34.76 μM, respectively." (PMID 41515395, 2025). "FA- and HA-modified CS-DDS showed up to a 1.5–3-fold increase in cellular uptake in FRα+ and CD44+ colorectal cancer cells, respectively." (PMID 41440901, 2025). "Consistent with other reports, apigenin has been demonstrated to be an effective agent for inhibiting cell migration in CD44+ prostate cancer cells and colorectal cancer cells (DLD1 and SW480)." (PMID 39997927, 2025).